PIEZO1 (piezo type mechanosensitive ion channel component 1 (Er blood group))
Diseases named in the same sentence as PIEZO1 in open-access papers (continued):
Sharing a sentence is not in itself a finding about the gene and the disease.
Cerebral ischemia (4 papers, 2021 to 2024). Restriction of arterial blood supply to the brain associated with insufficient oxygenation to support the metabolic requirements of the tissue. "It has also been shown that the expression of Piezo1 channels is increased after cerebral ischemia in rats." (PMID 36293444, 2022). "Past studies have shown that hypoxia-inducible factor 1-alpha (HIF1α) is an essential protein in Piezo1/calcium signaling, ferritin pendulous regulation, and cerebral ischemia, and HIF1α expression is increased in neurons and astrocytes after cerebral ischemia." (PMID 39539343, 2024). "Also, Piezo1 is proposed to be a vital factor that leads to cerebral ischemia-reperfusion injury." (PMID 34795840, 2021).
cholangiocarcinoma (4 papers, 2023 to 2025). A carcinoma that arises from the intrahepatic biliary tree (intrahepatic cholangiocarcinoma) or from the junction, or adjacent to the junction, of the right and left hepatic ducts (hilar cholangiocarcinoma). "For example, Mechanical stretch triggers PIEZO1 activation, which in turn promotes the metastasis of cholangiocarcinoma cells through the Hippo/YAP signaling pathway." (PMID 40977743, 2025). "Our analysis of pan‐cancer data from The Cancer Genome Atlas (TCGA) using the TIMER database revealed that FAM38A, encoding Piezo1, was overexpressed in a variety of cancers, notably BLCA, cholangiocarcinoma (CHOL), kidney renal clear cell carcinoma (KIRC), and liver hepatocellular carcinoma (LIHC)." (PMID 40667648, 2025). "Therefore, we confirm that PIEZO1 promotes GC progression primarily through the activation of the YAP1 signature, which is consistent with studies on cholangiocarcinoma." (PMID 37983931, 2023).
cystitis (4 papers, 2021 to 2023). Inflammation of the urinary bladder. "For example, PIEZO1 expression is found increased in experimental models of cyclophosphamide-induced cystitis and partial outlet obstruction, two conditions that are generally associated with increased bladder excitability." (PMID 37108490, 2023). "During chronic cystitis, mechanically activated Piezo1 promotes the flow of Ca2+ and Na+ into ICC-LCs." (PMID 35154133, 2022). "Other mouse studies have proposed (although not directly tested) roles for Piezo1 in partial bladder outlet obstruction, cystitis, and conditions that may arise from altered circadian expression of genes (including Piezo1), which are hypothesized to contribute to nocturia and enuresis." (PMID 34464353, 2021). "In rats with chronic cystitis, the NCX reverse mode in the bladder ICC-LCs were relatively activated and cooperated with Piezo1." (PMID 35154133, 2022). "GsMTx4(an inhibitor of Piezo1) can significantly improve the urodynamic abnormalities related to cystitis, significantly reduce the maximum bladder pressure (MBP), significantly extend the systolic interval (ICI), and relieve the symptoms of cystitis." (PMID 35154133, 2022). "We found that several MSC genes including Trpv1, Trpv4, Piezo1, and Piezo2 were all upregulated in both layers of the bladder (urothelium and detrusor), following chronic CYP-induced cystitis, but not acute CYP-induced cystitis." (PMID 35295484, 2021). "Lastly, though we attempted to study PIEZO1 activation in rats with CYP-induced cystitis, the within group variability due to the CYP treatment was too high to assess any changes related to PIEZO1 (data not shown)." (PMID 35295484, 2021). "In a cyclophosphamide (CYP) model of cystitis, we found that the gene expression of several candidate MSCs (Trpv1, Trpv4, Piezo1, and Piezo2) were all upregulated in the urothelium and detrusor following chronic CYP-induced cystitis, but not acute CYP-induced cystitis." (PMID 35295484, 2021).
edema (4 papers, 2019 to 2023). An abnormal accumulation of fluid beneath the skin, or in one or more cavities of the body. "Increased pulmonary vascular pressures in Piezo1fl/fl mice were associated with significant pulmonary edema and increased vascular permeability; however, endothelial-specific deletion of Piezo1 prevented both responses." (PMID 31186359, 2019). "For instance, excessive mechanical stretch during high tidal volume ventilation induces augmentation of endothelial Piezo1-mediated Ca2+ influx, and subsequently increases Ca2+-dependent calpain activity and result in pulmonary endothelial hyperpermeability and pulmonary edema." (PMID 36539808, 2022). "In summary, we identified a novel homozygous missense mutation: PIEZO1 c.5162 C>G (p.Ser1721Trp) that leads to LMPHM6, in a family with three adverse pregnancy outcomes due to nonimmune fetal hydrops." (PMID 35646098, 2022).
erythrocytosis (4 papers, 2020 to 2024). "The inclusion of patients with suspected PIEZO1 variants aims to deepen our understanding of their potential roles in erythrocytosis and other RBC disorders." (PMID 39085840, 2024). "Recently, pathogenic mutations in the PIEZO1 gene were noted in up to 4% of individuals with idiopathic erythrocytosis, in association with clinical or biological manifestations of hereditary xerocytosis (HX)(iron overload, splenomegaly, hemolysis, decreased venous p50)." (PMID 34021251, 2021). "In a large series of patients with HX and PIEZO1 mutations, 68% were not anemic; moreover, 7 adults had Hgb >16 g/dl, with two patients known to have erythrocytosis." (PMID 34021251, 2021). "Functionally, Piezo1-HX affects red cell energy metabolism and glycolysis, resulting in reduced BPG levels, conferring a high-oxygen affinity state, which explains the basis for erythrocytosis in this disorder." (PMID 34021251, 2021).
experimental autoimmune encephalomyelitis (4 papers, 2022 to 2025). An autoimmune demyelinating disease of the central nervous system that is produced experimentally in animals by the injection of homogenized brain or spinal cord in Freund's adjuvant. "In the experimental autoimmune encephalomyelitis model, Piezo1 was shown to suppress the expansion and/or function of regulatory T cells (Tregs) by limiting the TGF-β signaling pathway." (PMID 41281194, 2025). "Studies have shown that in a mouse model of MS, experimental autoimmune encephalomyelitis (EAE), mice with PIEZO1-deficient T cells exhibited milder disease progression, along with increased TGF-β signaling and an overall increase in regulatory T cell (Treg) numbers." (PMID 40703567, 2025). "Additionally, Piezo1 shows a selective tendency to restrain T‐reg cells, thus attenuating experimental autoimmune encephalomyelitis in Piezo1−/− mice." (PMID 39425504, 2024). "Inhibition of PIEZO1 in CD4+ T cells and/or regulatory T cells (Tregs) alleviated symptoms of experimental autoimmune encephalomyelitis (EAE)." (PMID 40703567, 2025).
Headache (4 papers, 2022 to 2023). Cephalgia, or pain sensed in various parts of the head, not confined to the area of distribution of any nerve. "Recent interest has been given to the emerging role of Piezo1 in meningeal nociception leading to migraine headache, with speculation into roles for modulating/mitigating VF mucosal injury." (PMID 36376494, 2022). "However, data presented in the current study, for the first time, show the absence of a sex difference in the activation of Piezo1 channels in meningeal afferents that have been implicated in the pathogenesis of migraine headache." (PMID 35012445, 2022).
Hydrocephalus (4 papers, 2023 to 2025). Hydrocephalus is an active distension of the ventricular system of the brain resulting from inadequate passage of CSF from its point of production within the cerebral ventricles to its point of absorption into the systemic circulation. "For instance, a model successfully induced hydrocephalus in mice by knocking out Piezo1 associated with the development and normal function of meningeal lymphatics, thereby impairing CSF drainage." (PMID 39908266, 2025). "Together, our study demonstrates that the brief preemptive overexpression of Piezo1 in lymphatics markedly reduces the severity of symptoms associated with hydrocephalus in a mouse model." (PMID 38528202, 2024). "However, lymphatic Piezo1 overexpression before disease induction effectively alleviated these hydrocephalus-associated symptoms." (PMID 38528202, 2024). "We next explored the potential therapeutic efficacy of activating lymphatic Piezo1 to decrease abnormal CSF accumulation in hydrocephalus." (PMID 38528202, 2024). "We further extended our findings toward suppressing the pathological phenotypes of mouse models of hydrocephalus and ventriculomegaly by targeting Piezo1 in mLVs." (PMID 38528202, 2024). "On days 10–11, we assessed the effect of lymphatic Piezo1 overexpression on hydrocephalus phenotypes, such as CSF physiology, ventricular volume and physical activity, in mice." (PMID 38528202, 2024). "Selective overexpression of Piezo1 in lymphatics or systemic administration of Yoda1 in mice with hydrocephalus or Down syndrome resulted in a notable decrease in pathological CSF accumulation, ventricular enlargement and other associated disease symptoms." (PMID 38528202, 2024). "The authors find that Piezo1 stimulation enhances meningeal lymphatics and boosts CSF drainage to treat hydrocephalus and ventriculomegaly, showing promise in Down syndrome and hydrocephalus models." (PMID 38528202, 2024). "Finally, Piezo1 overexpression in a hydrocephalus model alleviated ventricular enlargement and fluid buildup by restoring brain fluid outflow." (PMID 41099766, 2025). "In a mouse hydrocephalus model, activation of Piezo1, either via transgenic overexpression or treatment with the chemical agonist Yoda1, effectively alleviated the reduced physical activity caused by the disease, as demonstrated by improved performance in open field, rotarod, and mesh hanging tests." (PMID 41099766, 2025).
liver fibrosis (4 papers, 2023 to 2025). "In order to investigate functions of macrophage Piezo1 in liver fibrosis, myeloid-specific Piezo1 deficiency mice (Piezo1ΔLysM) were used in this study." (PMID 37908726, 2023). "In summary, the mechanosensitive cation channel Piezo1 plays a critical role in hepatic pathophysiology, where mechanical-stimuli-induced alterations in Ca2+ homeostasis contribute to the progression of liver fibrosis, cirrhosis, and cancer." (PMID 41017814, 2025). "Nevertheless, the levels of Piezo1 expression in liver fibrosis and cirrhosis vary, necessitating further investigation to elucidate Piezo1’s downstream signaling pathways and its molecular mechanisms in the treatment of liver fibrosis." (PMID 41017814, 2025). "In summary, as a Ca2+ influx channel that responds to mechanical stress, Piezo1 mediates a series of fibroblast movements upon activation, thereby forming a positive feedback loop that contributes to the progression of liver fibrosis and cirrhosis." (PMID 41017814, 2025). "The activation of Piezo1 ion channels regulates angiogenesis and fibroblast generation, promoting the progression of liver fibrosis into the common terminal pathway of chronic liver diseases." (PMID 41017814, 2025). "This study provides a preliminary explanation of the role of Piezo1 in the progression of liver fibrosis in macrophages." (PMID 41017814, 2025). "Collectively, these findings underscore the critical contribution of macrophage Piezo1 as a pivotal factor in liver fibrosis." (PMID 37908726, 2023). "In conclusion, our study revealed the key roles of macrophage Piezo1 in progression of hepatic fibrosis." (PMID 37908726, 2023). "Myeloid-specific Piezo1 knockout (Piezo1ΔLysM) attenuated liver fibrosis by decreased collagen deposition and epithelial-mesenchymal transition (EMT)." (PMID 37908726, 2023). "To investigate Piezo1 expression in liver fibrosis, we collected 20 human liver samples for slice staining." (PMID 37908726, 2023). "First, a positive correlation is observed between increased macrophage Piezo1 expression and liver fibrosis in both human and mouse samples." (PMID 37908726, 2023). "The progression of liver fibrosis, which was detected by H&E, Masson's and Sirius red staining, were significantly slowed down in Piezo1+/- mice compared with that in Piezo1+/+ mice." (PMID 37908726, 2023). "The aim of the study is to investigate the functions of macrophage Piezo1, a mechano-sensitive ion channel, in liver fibrosis." (PMID 37908726, 2023). "Piezo1 overexpression activates signaling crosstalk in other cells, such as inflammatory responses, and stimulates HSCs, transforming their phenotype into activated fibroblasts, which increases liver fibrosis and stiffness." (PMID 41017814, 2025). "In vivo, the results suggested that knockout of Piezo1 could inhibit the progression of liver fibrosis." (PMID 41020578, 2025). "However, how myeloid Piezo1 influence immune microenvironment and activation of HSCs during liver fibrosis needs further examinations." (PMID 37908726, 2023). "Next, we explored whether myeloid-specific Piezo1 has a role in T cell proliferation and activation during liver fibrosis." (PMID 37908726, 2023). "Additionally, the knockout of myeloid Piezo1 was found to suppress hepatic fibrosis by inhibiting macrophage recruitment, reducing inflammation, and impeding M1 polarization." (PMID 37908726, 2023). "The pivotal role of macrophage Piezo1 in liver fibrosis is substantiated in our investigation." (PMID 37908726, 2023). "Fourth, macrophage Piezo1 governs T cell activity and HSCs activation during liver fibrosis." (PMID 37908726, 2023). "Taking together, our results showed Piezo1 knockout in myeloid cells attenuate liver fibrosis." (PMID 37908726, 2023). "In this study, we aimed to investigate the functions of macrophage Piezo1 in hepatic fibrosis." (PMID 37908726, 2023). "We examined whether myeloid-specific Piezo1 effects on macrophage infiltration during liver fibrosis." (PMID 37908726, 2023).
liver fibrosis (continued). "Herein, macrophage Piezo1 could regulate fibroblast activation during liver fibrosis." (PMID 37908726, 2023). "In liver fibrosis and HCC, Piezo1 activation mediates Ca2+ influx, leading to activation of pro-fibrotic and pro-tumorigenic pathways, such as TGF-β and Hippo/YAP signaling, thus promoting disease progression." (PMID 41017814, 2025). "Piezo1 is essential for HSC activation and progression of liver fibrosis." (PMID 41017814, 2025). "Myeloid-specific Piezo1 regulates macrophage infiltration, inflammation, M1 polarization as well as synthesis and secretion of CTSS, which promotes HSCs activation and T cell activity during liver fibrosis." (PMID 37908726, 2023). "However, how macrophage Piezo1 influences liver fibrosis has not been reported." (PMID 37908726, 2023).
microcephaly (4 papers, 2015 to 2023). A congenital or acquired developmental disorder in which the circumference of the head is smaller than normal for the person's age and sex. "Mutations in DHCR7, encoding the penultimate enzyme in the pathway (downregulated 1.46-fold in Piezo1 KO brains) underlie Smith–Lemli–Opitz syndrome (SLOS), which includes symptoms of microcephaly, mental developmental delay, and hearing impairment." (PMID 36069933, 2022).
ovarian cancer (4 papers, 2022 to 2026). A primary or metastatic malignant neoplasm involving the ovary. "Hence, Piezo1 promotes ovarian-cancer growth and dissemination via a mechanical–Hippo/YAP–EMT pathway, and its inhibition or blockade represents a promising anti-metastatic strategy." (PMID 40821847, 2025). "Piezo1 is also highly expressed and mechanosensitive in ovarian carcinoma." (PMID 40821847, 2025). "Also, Piezo1 expression was higher in ovarian cancer tumor tissues than that in adjacent non-tumor tissues." (PMID 35942515, 2022).
Parkinson disease (4 papers, 2022 to 2025). A progressive degenerative disorder of the central nervous system characterized by loss of dopamine producing neurons in the substantia nigra and the presence of Lewy bodies in the substantia nigra and locus coeruleus. "In neurodegenerative diseases such as AD and Parkinson’s disease (PD), the dysfunction of Piezo1 is considered a major driving factor for neuronal injury and death." (PMID 41195420, 2025). "In addition, further studies are needed to investigate the role of Piezo1 channel‐mediated mechanical signaling in other neurodegenerative diseases, including Parkinson's disease, Huntington's chorea, and amyotrophic lateral sclerosis." (PMID 37366640, 2023). "In this context, altered PIEZO1 expression, whether increased or decreased, could hypothetically contribute to disrupted fluid dynamics or waste accumulation, as suggested in Alzheimer’s and Parkinson’s disease models." (PMID 40823415, 2025).